ATF3 (activating transcription factor 3)
Diseases named in the same sentence as ATF3 in open-access papers (continued):
Sharing a sentence is not in itself a finding about the gene and the disease.
infection (65 papers, 2010 to 2025). The state of being infected such as from the introduction of a foreign agent such as serum, vaccine, antigenic substance or organism. "We also found that in comparison with control larval infection strongly downregulated Atf3 gene expression, another transcription factor associated with Breg function, immune regulation, and homeostasis and therapies only moderately modulated mRNA levels." (PMID 40725240, 2025). "Mice deficient in ATF3 exhibit reduced survival rates and an increased bacterial load in the lungs after infection with S. pneumoniae." (PMID 38255898, 2024). "Differences in EGR1 and ATF3 transcriptional response kinetics and magnitude upon infection with different SARS-CoV-2 variants were confirmed via qPCR." (PMID 38305139, 2024). "Despite significant upregulation in response to ZIKV relative to mock infection, many of the immune response-associated genes displayed dampened induction and lower overall transcript abundance in ATF3 KO relative to WT." (PMID 39212382, 2024). "ATF3-mediated suppression of the innate cytokine storm abrogated the control of bacteria and causes high susceptibility to secondary infections." (PMID 38255898, 2024). "For modulation of infection and inflammation, ATF3 encodes a member of the ATF/cyclic adenosine monophosphate (cAMP) response element (CRE) binding (CREB) transcription factor family." (PMID 35370996, 2022). "In this study, ATF3 deficiency hindered ROS homeostasis in mice, resulting in diminished post-infection survival." (PMID 30214444, 2018). "The infection susceptibility of ATF3-deficient flies can be rescued by forced expression of Raw or dominant negative JNK, indicating that JNK hyper-activation is the main dysfunction in these flies." (PMID 28272390, 2017). "The role of ATF3 immune regulation and connections to infection associated diseases warrants further study." (PMID 21152039, 2010). "However, Raw expression rescued the susceptibility to infection caused by ATF3 depletion, suggesting that buffering intestinal JNK activity is critical for tissue regeneration and preventing organismal death." (PMID 28272390, 2017). "However, a significant increase in numbers of mitotic cells was observed in both ATF3- and Raw-deficient midguts after infection, as compared to controls." (PMID 28272390, 2017). "Hence, we conclude that depletion of ATF3 induced massive epithelial cell loss followed by intestinal barrier breakdown, and that this is the primary cause of fly susceptible to infection." (PMID 28272390, 2017). "Conversely, infection with M. vogae led to a downregulation of Atf3, a transcription factor involved in cellular stress responses, suggesting stress-induced modulation of the lymphoid microenvironment." (PMID 40725240, 2025). "After infection with Streptococcus pneumoniae (S. pneumoniae), ATF3 regulates GPB5 or forms a complex with JUN, thus promoting the production of inflammatory cytokines (TNF-α, IL-1β, IL-6, and IFN-γ)." (PMID 38255898, 2024). "During infection, ATF3 actively adjusts innate immunity by enhancing the expression of TNF-α, IL-1β, and IFN-γ, thereby facilitating bacterial clearance." (PMID 38255898, 2024). "The expression of ATF3 can be induced by various pathogen infections, including bacteria and viruses, indicating its universality on host defense mechanisms." (PMID 38255898, 2024). "AAV8-based infection restored ATF3 expression in the liver during the ADF process, without affecting food intake or body weight." (PMID 39872376, 2024). "Next, WT and ATF3 KO cells were mock-infected or infected with ZIKV at two different multiplicities of infection [moi; 1 and 10 plaque-forming unit (PFU)/cell]." (PMID 39212382, 2024). "Cells were harvested at 24 hours post-infection, and virus and ATF3 expression were examined by Western blotting and RT-qPCR." (PMID 39212382, 2024).
infection (continued). "Principal component analysis (PCA) revealed four clusters separating the samples by genotype (WT and ATF3 KO) and infection condition (mock and ZIKV)." (PMID 39212382, 2024). "RT‐qPCR analysis revealed a gradual increase in Atf3 mRNA expression at the 6th week post‐infection, peaking at the 9th week (p <0.001)." (PMID 39031798, 2024). "Here, we summarize the role of ATF3 during pathogen infection and discuss its potential impact within host defense mechanisms." (PMID 38255898, 2024). "Elevated ATF4 expression indicated that the ISR pathway was activated during ZIKV PRVABC59 infection, which in turn stimulated ATF3 expression and downstream targets like CHOP for stress management." (PMID 39212382, 2024). "Activating transcription factor 3 (ATF3) is a transcription factor that plays pivotal roles in cellular response to inflammation, infection, ER stress, metabolic changes, and oncogenesis." (PMID 39201329, 2024). "Subsequently, activated ATF3 then inhibits the transcription of the pro-inflammatory cytokine IL-6, thus promoting the progression of the infection." (PMID 38255898, 2024). "During episodes of bacterial sepsis, the host modulates its response to infection by upregulating or suppressing cytokines through ATF3." (PMID 38255898, 2024). "Our animal experiments revealed a gradual increase in ATF3 mRNA expression at 6 weeks post‐infection, peaking at 9 weeks, and decreasing thereafter, similar to the expression trend of α‐SMA." (PMID 39031798, 2024). "Early acute infection and A549 infected cells shared 150 upregulated genes including ATF3, a stress induced transcription factor, as well as other genes involved in the innate immune response such as MX1, DDX58/RIG-I, IFIT1, IFIT2, DHX58/MDA5, and OASL." (PMID 39065267, 2024). "Here, we infused 1 × 106 pfu/10 μL of Ad-ATF3 or Ad-hPGK (untransduced control) into the right lateral ventricles, and determined ATF3 protein levels in the ipsilateral cortices at 12 h to 2 days (2 d) after infection." (PMID 36768628, 2023). "Although all ATF3 KO mice died within 24 h, 60% of WT mice survived more than two days after infection." (PMID 35370996, 2022). "We found that the infection significantly upregulated the expression of Acod1 and its downstream genes (Atf3, Stat3, Nfe2l2 and Nrf2, etc.)." (PMID 36618398, 2022). "Overexpression of CXCL2, TNFAIP3, ATF3, and CXCL3 increased VEEV-TC-83 infection, suggesting rate limitation associated with these candidate proviral factors." (PMID 33788849, 2021). "In contrast, increased ATF3 expression via lentiviral infection of cDNA (oeATF3) can then lead to decrease the PCa cell proliferation in both C4–2 and CWR22Rv1 cells." (PMID 33390173, 2021). "ATF3 mRNA expression at the ipsilateral DRG of the infected paw was unaltered 30 days post-infection." (PMID 31138231, 2019). "We observed that ATF3 mRNA is induced several fold following infection with Pseudomonas entomophila (P.e)." (PMID 28272390, 2017). "In the first set of experiments, ATF3 was overexpressed in adult mouse DRG neurons through adenovirus (AV) mediated infection." (PMID 27581653, 2016). "Analyzing the differences in more detail, ATF3 was among the transcription factors whose up-regulation was significantly higher in response to live infection than stimulation with inactivated Salmonella in both cell types." (PMID 27000047, 2016). "The increase of ATF-3 expression at 21 dpi suggested the injury of neuronal cells at late phase of infection." (PMID 26070790, 2015). "Ifnar1−/− mice exhibited reduced concentrations of ALT compared to WT mice and a decreased induction of Atf3 mRNA in the liver after infection, confirming the central role of IFN-I signaling in mediating liver damage." (PMID 26588782, 2015). "Two stable clones derived from KMS-11 cells with suppressed basal expression levels of either ATF3 or ATF4 were established by infection with two different lentiviruses, each carrying a miRNA sequence targeting ATF3 or ATF4." (PMID 26636288, 2015).
infection (continued). "This ameliorated the virus-induced increase in concentrations of ALT in Sod1−/− mice upon infection and led to a reduction of Atf3 mRNA expression." (PMID 26588782, 2015). "Superoxide dismutase 2 (SOD2) and ATF3 are important anti-oxidative genes that were up-regulated to a greater extent in COPD pBECs after infection when compared with infected healthy pBECs." (PMID 23384071, 2013). "NaBu was proved to promote the sensitivity of OS cells to erastin-induced ferroptosis by upregulating the activating transcription factor 3 (ATF3) expression, a transcriptional repressor induced during inflammation and infection, which subsequently suppresses SLC7A11 transcription." (PMID 41301848, 2025). "Knockdown of Snhg15 during VEEV TC-83 infection resulted in the suppression of ten genes including Irf1, Junb, Atf3, Relb, Pim1, Hbegf, Ccl5, Ankrd33b, and H2-K2, all of which were also increased during TC-83 infection when the expression of Snhg15 increased in primary mouse astrocytes." (PMID 40463150, 2025). "Reduced ATF3 could lead to a less responsive stress adaptation, possibly affecting macrophage survival under stress conditions related to infection." (PMID 40637600, 2025). "Reduced SP2 and ATF3 may decrease inflammation further, dampening macrophage responses and limiting adaptation to stress within the infection environment." (PMID 40637600, 2025). "ATF3 has been reported to facilitate the generation of IL-17A in γδ T cells through macrophage-mediated secretion of IL-1β, thus modulating the response to infection." (PMID 38255898, 2024). "For instance, in ATF3-deficient bone marrow-derived macrophages (BMDM), the expression of IFN-β and other downstream components was upregulated compared to WT cells, and this attenuated LMCV and VSV*DG(Luc) replicon infections." (PMID 39212382, 2024). "However, Atf3 mRNA expression decreased by the 12th week post‐infection, with this declining trend persisting until the 18th week." (PMID 39031798, 2024). "In recent years, the function of ATF3 in the regulation of immune responses has been extensively studied, especially with regard to its expression and regulatory mechanism in host cells after pathogen infection." (PMID 38255898, 2024). "Similar to WT STm infection, genes involved in the regulation of immune responses (ATF3, BATF3, ETS2, IRF9, NFκB2, MAFA, TNFAIP3), effector functions, (CCL4, CD200L, CD40, CD72, CD80, IL18) and TLR signaling, (EAF2, TLR15, TRAF3IP2, TOLLIP) were upregulated after ΔprgH STm infection in both models." (PMID 37854334, 2023). "ATF3 KO mice displayed profound lung pathology during the infection." (PMID 35370996, 2022). "However, the count of bacterial colony-forming units (CFU) showed that the bacterial load was significantly reduced in WT, while ATF3 KO had less reduction during the 6-18 h infection process." (PMID 35370996, 2022). "Similarly, the protein level of Col1α1, MMP2, and α-SMA was also markedly decreased by ATF3-shRNAs infection." (PMID 33311456, 2020). "Activating transcription factor 3 (ATF3), which is induced by the infection of JEV, inhibits cellular antiviral signaling in Neuro-2a cells, suggesting that the ATF3 induction level might differ between Muar- and Mie/41/2002-infected Neuro-2a cells." (PMID 32629892, 2020). "ATF3 mRNA expression was assessed in DRG cells at the 30th day post-infection." (PMID 31138231, 2019). "In addition, it has been reported that ATF3 enhances pro-inflammatory cytokine production in response to infection by gram-positive pathogens such as Streptococcus pneumoniae, Listeria monocytogenes, and Staphylococcus aureus." (PMID 30214444, 2018). "ATF3 depletion enhances intestinal regeneration triggered by infection, but does not compensate for the loss of enterocytes and ATF3-depleted flies succumb to infection due to intestinal barrier dysfunction." (PMID 28272390, 2017).
infection (continued). "Interestingly, flies that overexpress ATF3 or Raw survive better than wild-type flies after infection with P. entomophila." (PMID 28272390, 2017). "However, significantly higher levels of ATF3 mRNA were produced in response to live S. Typhimurium 3 h post infection." (PMID 27000047, 2016). "The expression of ATF-3 improved significantly at late infection phase." (PMID 26070790, 2015). "Alternatively, ATF3 may work in conjunction with other TFs, allowing for shifts in gene expression profile during infection." (PMID 24357630, 2014). "Furthermore, ATF3 positively regulated inflammatory cytokines IL-6 and IL-12p40 might be able to contribute to the infection resolution." (PMID 35370996, 2022). "Notably, all of the upregulated genes (Atf3, Fosb, Nur77, Nurr1 and Arc) belong to the class of Immediate Early (IE) response genes that are rapidly co-induced in multiple cell types in response to external stimuli, such as infection and inflammatory signals." (PMID 34938672, 2021). "Moreover, ROS regulation by ATF3 varies based on bacterial species and infection stage." (PMID 30214444, 2018). "Thus, it was presumed that the similar ROS levels observed during infection with gram-positive bacteria in ATF3 KO mice resulted from defects in ROS inhibition and cytokine production, and thus failed to defend against E. coli through an inability to produce sufficient cytokines." (PMID 30214444, 2018). "To further test our hypothesis that ATF3 buffers JNK activity to control enterocytes apoptosis and maintain tissue integrity during infections, we suppressed JNK activity (BskDN) in ATF3-RNAi expressing flies and then assessed the incidence of smurf-positive flies upon infection." (PMID 28272390, 2017). "Also the expression of transcription factors was significantly modified by HHV-6A/6B infection, with an early increase of ATF3, JUN and FOXA2 by both species, whereas HHV-6A specifically induced a 15-fold decrease of POU2AF1, and HHV-6B an increase of FOXO1 and a decrease of ESR1." (PMID 29163428, 2017). "ATF3 deficiency can also lead to a decrease of the production and secretion of antimicrobial peptides, which contribute to intestinal epithelium defence mechanism in response to infection (data not shown)." (PMID 28272390, 2017). "Interestingly, Raw expression was induced in response to infection and this induction could be reduced by ATF3 depletion." (PMID 28272390, 2017). "The analysis of RNA-seq data from infections of A549 cells with each virus demonstrated enrichment of ISR-regulated genes, including ATF3, GADD34 (gene name PPP1R15A), and CHOP (gene name DDIT3)." (PMID 39861909, 2025). "MERS-CoV and HCoV-OC43 both induced ATF3, GADD34, and CHOP at increasing levels over the course of infection." (PMID 39861909, 2025). "In this study, we determined that peak ATF3 expression coincides with robust ZIKV protein and RNA expression at 24 hours after infection in A549 cells." (PMID 39212382, 2024). "Infection of Calu-3 cells followed by qRT-PCR analyses revealed that SARS-CoV-2 induces expression of multiple Wnt target genes including TCF4, c-jun, and ATF3." (PMID 40295745, 2024). "During the infection with ZIKV of A549 cells, ATF3 promotes the transcription of the RIG-I, STAT1, IRF9, and ISG15 genes while simultaneously inhibiting the transcription levels of IFNβ and IFIT2." (PMID 38255898, 2024). "Therefore, this review discusses the role of ATF3 in the regulation of cellular apoptosis, ferroptosis, and inflammatory responses, with a particular focus on the complex regulatory role of ATF3 in pathogen infections, and explains its bidirectional regulatory role in these processes." (PMID 38255898, 2024). "In a previous gene expression study, we observed that ZIKV PRVABC59 (ZIKVPR) infection in a neuronal cell line (SH-SY5Y) stimulated immune and stress response genes such as ATF3 and CHOP." (PMID 39212382, 2024).
infection (continued). "RNA-seq showed that the expression of ACOD1 and its downstream genes (HMOX1, TNFAIP3, TAP1, ATF3, and NRF2) was significantly upregulated post infection." (PMID 37256871, 2023). "We also found that WT and ATF3 KO mice had a comparable neutrophil number as reflected by s100a9 staining and Ly6G+/CD11b+ population in the FACS analysis in post-infection lung tissue sections." (PMID 35370996, 2022). "ATF3 also triggers filamentous (F-actin) to control cytoskeletal reorganization in macrophages, thereby leading to morphological changes critical to cell motility in the intra infection sites of the lung, which may lead to antimicrobial processes within the cells." (PMID 35370996, 2022). "Adult deletion of Tsc2 induced an upregulation of cJun-positive and Atf3-positive nuclei with a correlation between the amount of RATF-positive neurons and infection efficiency." (PMID 31182472, 2019). "The negative regulator of NF-κB gene promoters, ATF3, was already greatly induced by MAP at 1 hpi (5.1-fold) and also for the entire infection period." (PMID 31969876, 2019). "Enterocyte-specific ATF3 inactivation increases JNK activity and sensitivity to infection, a phenotype that can be rescued by Raw overexpression or JNK suppression." (PMID 28272390, 2017). "Here the authors show in adult Drosophila enterocytes that ATF3 regulates the expression of Raw, a JNK antagonist, to control intestinal regeneration and barrier function in response to infection." (PMID 28272390, 2017). "Some studies have demonstrated that upon infection, H. pylori activates the expression of a number of genes such as CagA, AKT, TNF-α, ATF3, IRX5, IL-6 and IL-8." (PMID 24069310, 2013). "Interestingly, the levels of the CHOP (DDIT3), DR5 (TNFRSF10B), ATF3, and SESN2 proteins were dramatically increased in CYB5R3-overexpressing H1299 and H1703 cells following Ad-CYB5R3 infection." (PMID 38253797, 2024). "Notably during infection with the mosquito-borne flavivirus Japanese encephalitis virus (JEV), ATF3 was shown to repress the expression of select interferon stimulated and autophagy genes which enhanced viral protein and RNA levels." (PMID 39212382, 2024). "Post-infection with uropathogenic Escherichia coli (UPEC), cytokines such as IL-1β, IL-6, and IFN-γ are significantly suppressed, while the bacterial load in the lungs and spleens of wild-type mice is substantially higher than in ATF3 knockout mice." (PMID 38255898, 2024). "ZIKV MR766 also induced ATF3 mRNA and protein expression, albeit at 48 hours post-infection compared to 24 hours for ZIKV PRVABC59 (data not shown)." (PMID 39212382, 2024). "The highest level of the ZIKV nonstructural protein NS1 was observed at 24 hours post-infection and correlated with peak ATF3 protein expression." (PMID 39212382, 2024). "Consistent with the tunicamycin-treated cells (data not shown), ATF3 protein and RNA expression were induced by infection in WT cells and absent in the ATF3 KO cells." (PMID 39212382, 2024). "However, since ATF3-driven antimicrobial signaling is also triggered by other immune cell subpopulations, such as innate lymphocytes and T cells, we think that the early response and macrophage-mediated antibacterial infection may exclude the effect of other immune cells’ response." (PMID 35370996, 2022). "While not significantly upregulated following infection, transcription of ATF3, CXCL3, CXCL8, and PTGS2 was at least partially dependent on EGR1." (PMID 35746681, 2022). "Further, after statistical validation, JUNB, ATF3 and EGR2 genes were attained, which may be used as potential biomarkers with Candida species infection." (PMID 35314002, 2022). "Depletion of TNFAIP3, ATF3, TAF7, and TRMT10C mildly to moderately reduced VEEV-TrD infection." (PMID 33788849, 2021).